PUF60 (poly(U) binding splicing factor 60)
Description:
DNA- and RNA-binding protein, involved in several nuclear processes such as pre-mRNA splicing, apoptosis and transcription regulation. In association with FUBP1 regulates MYC transcription at the P2 promoter through the core-TFIIH basal transcription factor. Acts as a transcriptional repressor through the core-TFIIH basal transcription factor. Represses FUBP1-induced transcriptional activation but not basal transcription. Decreases ERCC3 helicase activity. Does not repress TFIIH-mediated transcription in xeroderma pigmentosum complementation group B (XPB) cells. Is also involved in pre-mRNA splicing. Promotes splicing of an intron with weak 3'-splice site and pyrimidine tract in a cooperative manner with U2AF2. Involved in apoptosis induction when overexpressed in HeLa cells. Isoform 6 failed to repress MYC transcription and inhibited FIR-induced apoptosis in colorectal cancer. Isoform 6 may contribute to tumor progression by enabling increased MYC expression and greater resistance to apoptosis in tumors than in normal cells. Modulates alternative splicing of several mRNAs. Binds to relaxed DNA of active promoter regions. Binds to the pyrimidine tract and 3'-splice site regions of pre-mRNA; binding is enhanced in presence of U2AF2. Binds to Y5 RNA in association with RO60. Binds to poly(U) RNA.
Synonyms: FIR; ROBPI; SIAHBP1; VRJS
Tractability: Small molecule: a structure with a bound ligand is known; it has a high-quality binding pocket. PROTAC: UniProt records ubiquitination sites on it; ubiquitination databases record sites on it; its protein half-life has been measured.
Gene: Protein-coding gene on chromosome 8 (143,816,344 to 143,830,709, reverse strand). Ensembl gene ENSG00000179950.
Subcellular location: Nucleus
Subcellular location (Human Protein Atlas): Nucleoplasm
Pathways (Reactome):
Metabolism of RNA: mRNA Polyadenylation; mRNA Splicing - Major Pathway
Chromatin organization: CHD1 and CHD2 subfamily
Disease: Dengue Virus-Host Interactions
Gene Ontology:
Molecular function: cadherin binding; identical protein binding; protein binding; RNA binding; nucleic acid binding
Biological process: alternative mRNA splicing, via spliceosome; mRNA splice site recognition; regulation of alternative mRNA splicing, via spliceosome
Cellular component: nucleoplasm; nucleus
Genetic constraint (gnomAD): Loss-of-function variants: 10 observed, 57.42 expected, observed/expected ratio (o/e) 0.17, 90% interval 0.11 to 0.29. The upper end of that interval is the gene's LOEUF score, 0.29, which puts it in group 1 of 6, group 1 being the genes least tolerant of losing a copy. Missense variants: 371 observed, 737.35 expected, observed/expected ratio (o/e) 0.5, 90% interval 0.46 to 0.55. Synonymous variants: 353 observed, 300.16 expected, observed/expected ratio (o/e) 1.18, 90% interval 1.08 to 1.28.
Gene-disease validity (ClinGen):
ClinGen rates the evidence that PUF60 causes each of these diseases.
syndromic intellectual disability (autosomal dominant): Definitive. A intellectual disability that is part of a larger syndrome.
Homologues: Orthologues: macaque PUF60 (100% identical), chimpanzee PUF60 (99% identical), dog PUF60 (99% identical), mouse Puf60 (99% identical), rat Puf60 (99% identical), guinea pig PUF60 (93% identical), pig PUF60 (91% identical), zebrafish puf60a (82% identical), zebrafish puf60b (75% identical), Drosophila melanogaster hfp (54% identical), Caenorhabditis elegans rnp-6 (44% identical). Paralogues in human: PABPC1 (18% identical), RBMS2 (18% identical), RBMS3 (17% identical), PABPC4 (17% identical), RBMS1 (17% identical), PABPC3 (16% identical), PABPC1L (16% identical), ELAVL4 (14% identical), ELAVL1 (14% identical), ELAVL2 (14% identical), ELAVL3 (14% identical), SF3B4 (14% identical), and 12 more.
Diseases named in the same sentence as PUF60 in open-access papers:
PUF60 is named in the same sentence as 70 diseases in open-access papers, as found by Europe PMC text mining. Sharing a sentence is not in itself a finding about the gene and the disease. The quoted sentences say what the papers report.
breast carcinoma (12 papers, 2015 to 2025). "However, while a better outcome for PUF60 over-expressing OC patients was indicated in TCGA-OV transcriptomic data, others reported association of PUF60 over-expression with breast cancer progression through down-regulation of PTEN." (PMID 33194730, 2020). "Among these 12 CanCord34 genes, the knockdown of PUF60, EXOSC4, or BOP1 was accompanied by the loss of cell viability in breast cancer cell lines." (PMID 36497066, 2022). "PUF60 also contributes to breast cancer progression via the PUF60-dependent downregulation of PTEN, stimulating the PI3-kinase pathway." (PMID 36497066, 2022). "Thus, based on their tumorigenic characteristics presented in this study and their roles in other cancer types, we identified five new putative breast cancer RBPs: PUF60, TFRC, KPNB1, NSF, and SF3A3." (PMID 35453681, 2022). "Consequently, we identified five putative breast cancer RNA-binding proteins (PUF60, TFRC, KPNB1, NSF, and SF3A3) showing strong tumorigenic characteristics." (PMID 35453681, 2022). "The results indicated that 17 of the CanCord34 genes’ transcripts, proteins, or both could be detected in the secretomes and plasma vesicles, including the EXOSC4 and PUF60 proteins, in the breast cancer secretome datasets." (PMID 36497066, 2022). "PUF60 is also implicated in HBV infection and breast cancer." (PMID 32538777, 2020). "It has been reported that PUF60 has tumor promoting effects in breast cancer 49, but it remains to be investigated whether this effect of PUF60 depends on TERT signaling." (PMID 33061812, 2020). "It has been reported that PUF60 is overexpressed in various cancers, including bladder cancer, colon cancer, hepatocellular carcinoma, non-small cell lung cancer, breast cancer, esophageal cancer and renal cell carcinoma, and its overexpression is closely related to its development and progression." (PMID 37632669, 2024). "In addition, it was recently shown that PUF60 is part of a long non-coding RNA (lncRNA)-associated ribonucleoprotein (RNP) complex, which regulates breast cancer metastasis through modulation of a translational regulatory lncRNA (treRNA), which suppresses the translation of E-cadherin (CDH1) mRNA." (PMID 26497854, 2015). "Supplementary investigation of the molecular and cellular functions of these proteins identified PUF60 and SF3A3 as new spliceosome-related breast cancer RNA-binding proteins." (PMID 35453681, 2022). "The expression of PUF60 was highly correlated with TNM staging and lymph node metastasis in breast cancer." (PMID 32219041, 2020). "PUF60, an oncogene, is highly expressed in BC tissue samples, and its high expression is closely related to the high lymph node metastasis rate and TNM stage of breast cancer." (PMID 32964046, 2020).
Verheij syndrome (11 papers, 2018 to 2026). "PUF60 haploinsufficiency causes Verheij syndrome (VRJS), a multisystem developmental disorder characterized by intellectual disability, short stature, microcephaly, craniofacial dysmorphism, and cardiac, renal, and vertebral anomalies." (PMID 41596295, 2026). "Recent reports of rare diseases such as Verheij syndrome patients with congenital anomalies harboring FIR/PUF60 mutations, also in CHARGE syndrome." (PMID 41596295, 2026). "In summary, our results illuminate a previously unappreciated metabolic bottleneck underlying RNP-6/PUF60 deficiency and warrant the need for further investigation of vitamin B12 supplementation as a therapeutic strategy for Verheij syndrome." (PMID 41333426, 2025). "To this end, we collected blood samples from 8 Verheij syndrome patients (6 males and 2 females) and 3 age-matched non-PUF60 mutation controls (1 male and 2 females) and performed metabolomic and lipidomic analyses with plasma." (PMID 41333426, 2025). "We propose a reclassification of PUF60-associated disorders since the clinical features of our patients are milder than the classical Verheij syndrome phenotypes." (PMID 38396730, 2024). "Several case series have identified PUF60 as the monogenic cause of Verheij syndrome and mainly reiterated the phenotypic findings." (PMID 38396730, 2024). "Yamada M, Uehara T, Suzuki H, Takenouchi T, Kosaki K. Protein elongation variant of PUF60: Milder phenotypic end of the Verheij syndrome." (PMID 37420288, 2023). "PUF60 is essential, and heterozygous loss of function causes Verheij syndrome, which is characterized by severe developmental abnormalities in most patients." (PMID 32538777, 2020). "Given that rnp-6(G281D) is a specific hypomorphic allele, we investigated whether VB12’s benefits extend to broader forms of RNP-6 insufficiency that mimic the partial loss-of-function features of PUF60 pathogenic variants in Verheij syndrome." (PMID 41333426, 2025). "Heterozygous variants in the Poly(U) Binding Splicing Factor 60kDa gene (PUF60) have been associated with Verheij syndrome, which has the key features of coloboma, short stature, skeletal abnormalities, developmental delay, palatal abnormalities, and congenital heart and kidney defects." (PMID 38396730, 2024). "Microdeletions in 8q24.3 specifically PUF60 are linked to the rare Verheij syndrome." (PMID 37189911, 2023). "Through global identification of PUF60-regulated exons, we have recently characterized splicing abnormalities in cells overexpressing PUF60 that contained germ-line RRM missense mutations found in Verheij syndrome (also known as or PUF60 deficiency, PD, or 8q24.3 microdeletion syndrome)." (PMID 32664474, 2020). "Hypomorphic mutations of PUF60 are known to cause a rare genetic disease called Verheij syndrome." (PMID 32538777, 2020). "Here, we investigate Verheij syndrome (VRJS), a rare disease caused by mutations in the core splicing factor PUF60." (PMID 41333426, 2025). "Defects and mutations in PUF60 or CHD7 have been identified in human congenital disorders, specifically Verheij syndrome and CHARGE syndrome." (PMID 41596295, 2026). "Heterozygous pathogenic variants in PUF60 are the cause of Verheij syndrome (MIM# 615583), and PUF60 haploinsufficiency plays a role in 8q24.3 deletion syndrome." (PMID 40796658, 2025). "Xu Q, Li CY, Wang Y, Li HP, Wu BB, Jiang YH, Xu X. Role of PUF60 gene in Verheij syndrome: a case report of the first Chinese Han patient with a de novo pathogenic variant and review of the literature." (PMID 37420288, 2023). "Verheij syndrome is a rare microdeletion syndrome of chromosome 8q24.3 that harbors PUF60, SCRIB, and NRBP2 genes." (PMID 30352594, 2018). "This again supports the much milder phenotype of pathogenic PUF60 variants in our patients that does not include the full picture of classical Verheij syndrome." (PMID 38396730, 2024).
Verheij syndrome (continued). "Hence, we propose to reclassify this entity as PUF60-related neurodevelopmental disorders with additional multi-system involvement and delineate mild PUF60-related neurodevelopmental disorders from classical Verheij syndrome." (PMID 38396730, 2024). "As our five patients showed less-severe phenotypes than classical Verheij syndrome, particularly with the absence of key features such as coloboma or palatal abnormalities, we propose a reclassification as PUF60-related neurodevelopmental disorders with multi-system involvement." (PMID 38396730, 2024).
developmental delay (6 papers, 2017 to 2024). "In one of these families, the same likely pathogenic variant in PUF60 was identified as the cause of developmental delay in two affected brothers." (PMID 39039281, 2024). "In this report, we describe a new case of VRJS with developmental delay, cardiac-, and renal abnormalities, caused by a heterozygous pathogenic PUF60 variant." (PMID 38273166, 2024). "PUF60 deficiency (PD) causes a developmental delay coupled with intellectual disability and spinal, cardiac, ocular and renal defects, but PD pathogenesis is not understood." (PMID 29788428, 2018). "The clinical and molecular data we observed in 12 patients suggest that variants in PUF60 cause a syndrome characterized by short stature, developmental delay, dysmorphic facial features and structural malformations of the heart, eye and variably other organs." (PMID 28327570, 2017). "We conclude that the facial features associated with PUF60 might be recognized independently, but the diagnosis is more likely to be considered in a child with short stature, developmental delay and additional malformations described." (PMID 28327570, 2017). "Index patient 5[II:1] presented with both pathognomonic (developmental delay and short stature) and variable (coloboma, microphthalmia, heart defect) manifestations seen in the proposed PUF60 phenotype." (PMID 33418956, 2021). "In 2013, patients with microdeletions of chromosome 8q24.3 including PUF60 were found to have developmental delay, microcephaly, craniofacial, renal and cardiac defects." (PMID 28327570, 2017).
gastric cancer (6 papers, 2015 to 2025). A primary or metastatic malignant neoplasm involving the stomach. "In addition, it is involved in regulation of MYC transcription, and it is known that certain PUF60 splice variants are overexpressed in ovarian and gastric cancer." (PMID 26497854, 2015). "In conclusion, it was proved that PUF60 promoted the inhibition of apoptosis of GC cells and enhanced the resistance of gastric cancer cells to chemotherapy drugs." (PMID 39781520, 2025). "Copy number gains of PUF60 show a strong positive correlation with expression in gastric cancer and in ovarian cancer." (PMID 26360582, 2015). "In addition, the knockdown of PUF60 significantly reduced the proliferation of human gastric cancer cells and increased sensitivity to chemotherapy drugs, such as 5-FU and cisplatin (CDDP)." (PMID 39781520, 2025). "Mechanistically, PUF60 enhances chemotherapy resistance in gastric cancer (GC) cells by actively excluding chemotherapy drugs via the recombinant ATP Binding Cassette Transporter A1 (ABCA1) and ATP Binding Cassette Subfamily C Member 1 (ABCC1)." (PMID 39781520, 2025). "FIR family (FIR, FIRΔexon2, and PUF60), Snai1, and BRG1 increased, but FBW7 and E-cadherin decreased in human gastric cancers, as shown by immunohistochemical staining; however, the expression of BRG1 was reduced in some cases." (PMID 32071290, 2020). "There is currently no existing literature on the knockdown of PUF60 in gastric cancer, and this limitation may be attributed to the specificity of PUF60." (PMID 39781520, 2025).
bladder cancer (5 papers, 2020 to 2025). "In this study, we investigated the potential association between PUF60 expression and clinicopathological characteristics in bladder cancer and analyzed the potential of PUF60 to be a new biomarker for malignant phenotypes and poor prognosis in bladder cancer." (PMID 33117697, 2020). "The expression of PUF60 was significantly higher in tumor tissues, while high PUF60 expression was associated with malignant phenotypes of bladder cancer and shorter survival time." (PMID 33117697, 2020). "To clarify the underlying molecular mechanism by which PUF60 promoted bladder cancer growth, we analyzed the association between genome-wide expression profiles and PUF60 mRNA expression based on the data from GSE13507." (PMID 33117697, 2020). "In summary, we found that PUF60 was highly expressed in bladder cancer cells and associated with malignant phenotypes of bladder cancer." (PMID 33117697, 2020). "Our previous work proved that PUF60 was highly expressed in bladder cancer, but it was unclear the association between PUF60 mRNA expression and bladder cancer phenotypes, such as histopathological type, T stage, grade and molecular subtypes." (PMID 33117697, 2020). "To further clarify the potential underlying mechanism of PUF60-regulated bladder cancer cell growth, we selected GSE1357 dataset, which included the most samples of primary bladder cancer and intact clinical information of patients in all the datasets, to conduct gene expression profile analysis." (PMID 33117697, 2020). "Hence, we analyzed the association between PUF60 mRNA expression and molecular subtypes, grade, N stage or T stage of TCGA bladder cancer expression data." (PMID 33117697, 2020). "Collectively, our findings offer new insights into the understanding of the pro-tumorigenic role of PUF60 and its underlying mechanism involved in bladder cancer growth, and suggest that the PUF60/AURKA axis may provide prognostic biomarkers and therapeutic targets for bladder cancer patients." (PMID 33117697, 2020). "Furthermore, we found high PUF60 mRNA expression was associated with more malignant histological subtypes, higher pathological grade, advanced T stage and malignant molecular subtypes in bladder cancer." (PMID 33117697, 2020). "Mechanistically, this relationship was attributed to the transcriptional regulation of aurora kinase A (AURKA) by PUF60 on bladder cancer cell behavior." (PMID 39132499, 2024). "Although PUF60 is poorly studied in the context of cancer, its high expression has been detected in bladder cancer." (PMID 39132499, 2024). "We conducted Kaplan–Meier survival analysis according to the PUF60 mRNA expression of TCGA dataset in bladder cancer patients." (PMID 33117697, 2020). "To investigate the biological functions of PUF60 in bladder cancer, we detected the protein expression of PUF60 in five bladder cancer cell lines (5637, UM-UC-3, T24, Biu87, J82) by western blot." (PMID 33117697, 2020). "We found mRNA expression of AURKA, CDCA8, CDC20 were decreased upon knockdown of PUF60 by its specific siRNA, indicating that they are the potential downstream targets of PUF60 in bladder cancer (indicated by the arrows)." (PMID 33117697, 2020). "To further verify the expression of PUF60 in bladder cancer, we collected the published RNA-sequencing or microarray data of bladder cancer from Oncomine database and GEO database, which include four datasets containing both normal and carcinoma tissues." (PMID 33117697, 2020). "Overexpression of PUF60 significantly promoted cell viability and colony formation in bladder cancer cells, while treatment with AURKA specific inhibitor reversed this promotive effect." (PMID 33117697, 2020). "We found that the mRNA expression of PUF60 was significantly higher in basal bladder cancer tissues, which was a malignant molecular subtype with poor survival." (PMID 33117697, 2020).